MITF (melanocyte inducing transcription factor)
Diseases named in the same sentence as MITF in open-access papers (continued):
Sharing a sentence is not in itself a finding about the gene and the disease.
melanoma (continued). "Taken together with earlier published data, the evidence suggests that there are distinct roles for PAX3 and MITF in melanoma progression and melanoma cell migration, thus providing supporting evidence for one of the key predictions of the genetic switch theory." (PMID 24062982, 2013). "However, no publications to date have explored PRMT5 or its relationship with MITF and cell cycle regulatory proteins in primary melanoma specimens." (PMID 24098663, 2013). "If we can determine more precisely what influences different MITF levels in melanoma or if we could modulate MITF levels themselves, we might be able to better predict the behavior and progression of melanoma." (PMID 24039954, 2013). "Additionally, MITF, regulating melanocytes and melanoma development, has also been reported as a factor supporting melanoma stem cell properties." (PMID 23762150, 2013). "Interestingly, in two other “lower MITF” expressing melanoma cell lines (i.e., NZM9 and NZM40) there were undetectable levels of POU3F2 expression." (PMID 24062982, 2013). "Our recent silencing experiments further indicate that melanoma cells exert defects in proliferation when both BRG1 and BRM are depleted, which could be attributed to the loss of MITF expression." (PMID 23349796, 2013). "Thus, occupancy of BRG1 on the ML-IAP promoter is dependent on expression of MITF in these melanoma cells." (PMID 23480510, 2013). "Meanwhile, we showed that melanoma cells could undergo premature senescence upon MITF depletion or upon chemotherapy treatments." (PMID 24344100, 2013). "However and irrespective of their invasive capacities, a considerable proportion of melanoma samples (in our study nearly 50%) have high MITF and correspondingly high miR-211 expression levels compared to healthy cells." (PMID 24039954, 2013). "Several experimental approaches were used to investigate whether PAX3 and MITF expression and function were independent in melanoma cells and tissues." (PMID 24062982, 2013). "In addition, we show that in melanoma cell lines with lower levels of MITF expression, knockdown of PAX3 expression inhibits melanoma cell migration, whereas in melanoma cell lines with higher levels of MITF, knockdown of MITF enhances cell migration." (PMID 24062982, 2013). "Other prominent examples include MITF in melanoma and NKX2-1 (TTF1) in lung cancer." (PMID 24040285, 2013). "Analysis of MITF expression in melanoma cell lines, as well as melanoma tissues reveals marked variability in expression level, with some melanoma cell lines expressing up to 10-fold higher levels of MITFm, a melanocyte-specific isoform of MITF, than in other melanoma cell lines." (PMID 24062982, 2013). "Thus, authors concluded that MITF acts as the key molecular switch between human melanoma initiating cells and their differentiated progeny." (PMID 22984562, 2012). "Functionally, MITF serves as a master regulator of melanocyte development and a melanoma oncogene." (PMID 22848417, 2012). "BL6-B16 melanoma cells were co-transfected with MITF and PIAS3." (PMID 22316093, 2012). "Furthermore, MITF is also the master regulator for DNA replication, proliferation and genomic stability of melanoma cells and its reduction leads to DNA damage and defective cell replication." (PMID 22412813, 2012). "Regulation of CDK2 by MITF is essential for melanoma clonogenic growth." (PMID 22848417, 2012). "Interestingly, inhibition of MITF in malignant melanoma cells increases the expression of stem cell marker OCT4." (PMID 22815634, 2012). "In normal melanocytes, MITF induces cell cycle arrest, whereas in melanoma cells, mutant B-Raf may stimulate MITF transcription while this stimulation of transcription does not occur in normal melanocytes." (PMID 23006971, 2012). "Actually, it was proposed that MITF acts as lineage survival oncogene in melanoma." (PMID 21860617, 2012).
melanoma (continued). "We propose when metastasis has already occurred, preferentially inhibiting cell growth outweighs the benefit of fighting the invasive potential of melanoma, and as such, inhibiting MITF may improve patient survival." (PMID 22927992, 2012). "These events generated one hypothesis for the mechanism in which MITF can suppress melanoma metastasis." (PMID 21860617, 2012). "In addition to being a melanoma oncogene, depletion of MITF has been reported to induce arrest, senescence and cell death in melanoma identifying it as a potential target for therapy." (PMID 22316093, 2012). "MITF knockdown also reduced the expression of KIT in MALME-3M melanoma cells." (PMID 22570637, 2012). "Taken together, MITF has two-faced functions in melanoma development and progression, and strict regulation of MITF in its expression and/or activity is likely to switch melanocytes to melanoma cells." (PMID 22046555, 2011). "BCL-2 is overexpressed in melanoma: Factors including NRas and MITF may also contribute to increased Bcl-2 activity." (PMID 21479172, 2011). "However, the expression level of MITF in melanomas is significantly lower than that in normal melanocytes, and higher expression level of MITF in melanoma represses cell proliferation even in the presence of oncogenic BRAF." (PMID 22046555, 2011). "SNAI2 has been reported to be a key player for epithelial-mesenchymal transition (EMT), which is a crucial phenomenon during invasion, metastasis of melanoma, by repressing E-cadherin transcription and stimulating fibronectin expression, and MITF directly activates the transcription level of SNAI2." (PMID 22046555, 2011). "Several studies provide evidence that MITF serves as an oncogene in human melanoma." (PMID 20163701, 2010). "Interestingly, melanoma metastases show significantly less PAX3-positive than MITF-positive cells, and generally these were weakly stained for PAX3." (PMID 20421967, 2010). "Fourth, amplification of chromosome 3p and hypo-methylation of PAX3 together may elevate MITF expression in melanoma, which may up-regulate the downstream targets of MITF." (PMID 20925909, 2010). "According to this model, it is extremely important to regulate MITF expression in melanoma cells." (PMID 20644734, 2010). "We therefore assessed whether SOX10, which positively regulates MITF and whose transcription markedly increases in melanocytes and melanoma cells in which ATF2 expression is inhibited, may mediate ATF2 effect on MITF transcription." (PMID 21203491, 2010). "The rate of circulating MITF detection was higher with increasing melanoma stages." (PMID 20163701, 2010). "Primary melanoma specimens that exhibit a high nuclear ATF2-to-MITF ratio were found to be associated with metastatic disease and poor prognosis, further substantiating the significance of MITF control by ATF2." (PMID 21203491, 2010). "Given that ATF2 negatively regulates MITF in melanocytes of mouse and human tissues and in related melanocyte cell lines, we asked whether ATF2 also regulates MITF in human melanoma cells." (PMID 21203491, 2010). "A similar observation was made in a porcine model of spontaneously regressing melanoma in which MiTF was noted to be significantly downregulated during the regressive phase of the melanoma and upregulated during the progressive phase suggesting a central role for this protein in melanoma biology." (PMID 20174581, 2010). "Continued expression of MITF has been shown to be essential for melanoma cell proliferation and survival and, in fact, MITF has been proposed to act as a lineage survival oncogene in melanoma." (PMID 20644734, 2010). "MiTF is often amplified in advanced melanomas and functions as an oncogene." (PMID 21209915, 2010). "Notably, the melanocytes and 2/4 melanoma cell lines revealed ATF2 effect on MITF expression is SOX10-dependent (WM1361, WM793)." (PMID 21203491, 2010). "Consistent with this, there is less MITF expressed in melanoma cells than in normal melanocytes." (PMID 20644734, 2010).
melanoma (continued). "Whether it plays a role in melanocyte differentiation and melanoma progression, like other melanocyte-specific genes such as MITF, is an interesting matter for future studies." (PMID 20975957, 2010). "MiR-137 has previously been shown to target MITF in melanoma cells." (PMID 20644734, 2010). "The absence of miR-137 in 501mel cells might be explained by mutations in the miR-137 gene itself as has been shown to be the case in other melanoma cells, thus allowing high levels of MITF expression." (PMID 20644734, 2010). "MITF-Mdel, a novel melanocyte/melanoma-specific isoform of MITF-M, may serve as a potential candidate biomarker for diagnostic and follow-up purposes in melanoma." (PMID 20163701, 2010). "Both MITF-Mdel and MITF-M levels of expression in frozen melanoma tissue samples were significantly higher than those in melanoma cell lines (P = 0.0001), PBMCs from normal donors (P < 0.0001) and all of the non-melanoma cell lines (P < 0.0001)." (PMID 20163701, 2010). "Finally, MiTF, a key transcription factor in survival, maintenance and differentiation of melanocytes is detected in most malignant melanomas and the gene is amplified in 10 to 20% of cases of metastasis." (PMID 20174581, 2010). "Analysis of a MITF-Luc construct harboring a mutant SOX10 binding site revealed that ATF2 inhibition no longer elicited increased MITF transcription in human melanocytes or in melanoma cells." (PMID 21203491, 2010). "Particularly relevant to melanoma is the regulatory role that SWI/SNF enzymes play in promoting neural crest migration and differentiation as well as SWI/SNF interactions with Microphthalmia -Associated Transcription Factor (MITF), a lineage survival oncogene in melanoma." (PMID 20969766, 2010). "Lower expression in 501mel might be a factor allowing a high level of MITF expression in this melanoma cell type." (PMID 20644734, 2010). "Effects on the endogenous human MITF gene were also determined in melanoma cells." (PMID 20644734, 2010). "Here we demonstrate that high nuclear ATF2/MITF ratios are associated with poor prognosis in primary melanomas, but not with metastatic melanomas." (PMID 21203491, 2010). "Both segment 9 CNV and MITF mRNA expression undergo melanoma-specific amplification." (PMID 20925909, 2010). "Importantly, ATF2-dependent negative regulation of Sox10 and consequently of MITF seen in melanocytes, but only in about 50% of the 18 melanoma cell lines studied here." (PMID 21203491, 2010). "Notably, MeWo and 501Mel lines are known to express high MITF levels compared to other melanoma lines, suggesting these cells harbor distinct mechanisms that preclude negative regulation of MITF by ATF2." (PMID 21203491, 2010). "Yet, the role of MITF in early stages of melanoma development remains largely unexplored." (PMID 21203491, 2010). "A number of mechanisms have been postulated to alter MITF expression in melanoma." (PMID 20041153, 2009). "Ten E-boxes found in 9 miRNA genes are bound by MITF in a melanoma cell line." (PMID 19881911, 2009). "Furthermore, the MITF gene is amplified in 10-15% of melanomas carrying a mutated BRAF, supporting the view that continued expression of MITF is essential in melanoma cells." (PMID 19828018, 2009). "Besides several findings of utmost importance for general miRNA research, they were able to determine nine miRNAs (e.g., miR-146a, miR-221/222, and miR-363) that are highly likely to be regulated by MITF and seem to be specific to melanoma." (PMID 19638982, 2009). "In this study, our gene expression profiling and knockdown experiments provided evidence that a core network of MITF-mediated transcription formed a significant component of a gene signature that correlated with the invasive potential of metastatic melanoma cell lines in vitro." (PMID 20041153, 2009).
melanoma (continued). "BRN2 has been reported to be a negative regulator of MITF in melanoma cells, yet we were unable to show any correlation between MITF and BRN2 transcription in this study, with any potential correlation tending towards positive rather than negative at the transcript level." (PMID 20041153, 2009). "Indeed, high MITF levels have been demonstrated to exert an anti-proliferative activity in melanoma cells." (PMID 19828018, 2009). "Overall, the question of whether MITF may exert a pro-survival effect or growth inhibition in melanocytes and melanoma is still open and not yet fully understood." (PMID 19828018, 2009). "The authors speculated that MITF might be a new prognostic marker in intermediate-thickness malignant melanoma." (PMID 19828018, 2009). "Thus, MITF is a sensitive marker of the melanocytic lineage, useful to study melanoma progression in the pig." (PMID 18442364, 2008). "Furthermore, we found that BRAF depletion resulted in reduced MITF mRNA expression in melanoma cells." (PMID 18628967, 2008). "Notably, the induction of BRN2 through MEK and ERK in melanoma cells appears to be fundamental to the ability of V600EBRAF to regulate MITF in these cells." (PMID 18628967, 2008). "MITF gene amplification is involved in melanoma progression." (PMID 18958307, 2008). "MITF has been described as a highly sensitive immunohistochemical marker for melanoma diagnosis." (PMID 18958307, 2008). "Here we describe another intriguing aspect of MITF regulation by oncogenic BRAF in melanoma cells." (PMID 18628967, 2008). "Thus, the cellular circuits in which MITF is engaged are clearly complex and when and how MITF contributes to melanoma development are open questions." (PMID 18211678, 2008). "Importantly, MITF depletion in melanoma cells blocked CDK2, p21Cip1 and CDK4 expression even though ERK was not inhibited." (PMID 18628967, 2008). "The decrease in MITF protein was due to reduced MITF mRNA expression as determined by quantitative RT-PCR and together these findings clearly demonstrate that in melanoma cells BRN2 is required for MITF expression downstream of oncogenic BRAF." (PMID 18628967, 2008). "Thus, in apparent contradiction to our previous findings, these data suggest that ERK activation is necessary for MITF expression in melanoma cells expressing oncogenic BRAF." (PMID 18628967, 2008). "Furthermore, the MITF gene is amplified in 10–15% of melanomas in which BRAF is mutated, supporting the view that continued expression of MITF is essential in melanoma cells." (PMID 18628967, 2008). "Notably, approximately 20% of melanomas exhibit MITF amplification." (PMID 41492362, 2026). "While these results aligned with previous studies, they highlighted the complexity of immune–melanoma interactions, suggesting that other immune or tumor-related factors may play key roles in modulating MITF expression, warranting further mechanistic investigation." (PMID 39976551, 2025). "Additionally, AXIN1 expression was increased by HH044, leading to lower β-catenin levels and thus preventing the activation of canonical signaling implicated in increasing the expression of genes such as MITF and APE-1, which protect melanoma from cellular damage from reactive oxygen species." (PMID 40574005, 2025). "Interestingly, in melanoma, GSK-3β negatively regulates the stabilization of microphthalmia-associated transcription factor (MITF) as well as the Wnt/β-catenin and PI3K/AKT pathways, which promote cancer cell survival, proliferation, and resistance to apoptosis." (PMID 39948552, 2025). "Additionally, experiments using B16F10 melanoma cells demonstrated a dose-dependent reduction in melanin production, accompanied by a decrease in the expression of melanogenesis-related genes, including MITF, TYR, TRP-1, and TRP-2." (PMID 40565189, 2025).
melanoma (continued). "Additionally, inhibiting FAO in MYC+ melanoma cells could effectively reduce lymph node metastasis favored by MITF, which provided a potential therapeutic approach in melanoma dissemination." (PMID 40376583, 2025). "Melanomas with a high proliferative index show high MITF expression; as SOX10 regulates the MITF pathway, it may suggest that invasion in oral melanoma occurs due to low MITF levels and high ZEB1 expression or through direct activation of the activity inhibitory melanoma (MIA) to invasion." (PMID 41012776, 2025). "Furthermore, in B16-F10 melanoma cells, Mb-ME suppresses melanogenesis by reducing melanin secretion and cellular melanin content, although it does not directly affect tyrosinase activity or the expression of key melanogenic regulators such as MITF and TYRP1." (PMID 40076896, 2025). "Therefore, the downregulation of MITF in melanoma cells with enhanced HOXA1 expression may lead to melanocyte de-differentiation and thus an invasive phenotype due to the upregulation of TGF-β activation." (PMID 39858044, 2025). "The effects of RAF/RAS mutations on the melanoma metabolism include stimulating MYC and HIF1α signaling to promote glycolysis, as well as the inhibition of mitochondrial oxidative phosphorylation (OXPHOS) by repressing MITF and PGC1α, and promoting fatty acid synthesis." (PMID 38397192, 2024). "Interestingly, a growing body of evidence indicates that sphingolipids might contribute to melanoma dedifferentiation via the regulation of MITF." (PMID 39136013, 2024). "In addition, immunofluorescence assays revealed a reduction in MITF following Bcl-2 overexpression, suggesting that Bcl-2 may be a regulator of MITF in the context of melanoma." (PMID 39594467, 2024). "However, the correlations of MITF expression with immune responses in patients with immunological diseases or cancers, including melanoma, and with the response to immune checkpoint inhibitors (ICIs) used to treat various tumor types have recently been investigated." (PMID 38351314, 2024). "Taken together our findings have profound translational implications because we identified a new MITF/miR-579-3p regulatory network that impacts on melanoma proliferation, differentiation and drug resistance and whose targeting may provide a novel therapeutic strategy for BRAF-mutant melanomas." (PMID 38472212, 2024). "Accordingly, a time and dose-dependent selection of melanoma cells in the presence of a BRAFi, resulted in the early phases of selection at low doses of drug exposure in strong upregulation of the levels of both miR-579-3p and MITF together with markers of differentiation." (PMID 38472212, 2024). "Thus, the low/high MITF ratio could have an essential role in the switch between dedifferentiated and differentiated melanoma cells." (PMID 39199632, 2024). "Furthermore, enrichment of microRNA (miR)-100-5p and miR-125b-5p was detected in the “MITF-low” cluster of melanoma samples in TCGA, and among the evaluated tumor patients, the expression of these miRs was higher in the immunotherapy responders than in the nonresponders." (PMID 38351314, 2024). "In addition, we could show that a pharmacological inhibitor of TPC2, SG-094 likewise results in a reduction of MITF in SK-MEL-5 as well as in other melanoma lines." (PMID 39562548, 2024). "Indeed, the human melanoma cell lines tested in this study have varying baseline levels of MITF." (PMID 39736644, 2024). "However, recent studies suggest that the role of MITF may extend beyond melanoma cells and melanocytes to other cell types." (PMID 38351314, 2024).